TGFB1 (transforming growth factor beta 1)
Diseases named in the same sentence as TGFB1 in open-access papers (continued):
Sharing a sentence is not in itself a finding about the gene and the disease.
breast cancer (continued). "TGFB1 signalling has also been implicated in susceptibility to breast cancer, where an association between breast cancer risk and the TGFB1 L10P gene polymorphism was reported by the Breast Cancer Association Consortium." (PMID 33761981, 2021). "In addition, the authors show that an upregulation of fibronectin, caused by cytokine TGFβ1 released from breast cancer-derived EVs, facilitated the adhesion of breast cancer cells to the liver microenvironment." (PMID 33777909, 2021). "The transcript variant (TGFB1):c.29C > T (p.Pro10Leu) is a risk factor for breast cancer." (PMID 32823908, 2020). "Allelic variants of the TGFB1 gene were also demonstrated to increase the risk of breast cancer." (PMID 31205821, 2019). "The same study observed that SNP rs1982073 in TGFB1 could exert its effect on gene expression by altering interaction with miR-187, and CC carriers of rs1982073 exhibited an increased risk of breast cancer (OR = 1.4, CI = 1.1–2.0; p = 0.04)." (PMID 30897768, 2019). "Interestingly, TGFβ1/SMAD signaling can also promote Snd1 (p100) expression which can facilitate epithelial to mesenchymal transitions (EMT) in mammary tumor cell lines, a causal event in tumor cell migration and invasion." (PMID 26633036, 2015). "Accordingly, for TGFB1*T29C polymorphism with the observed allele frequencies in the western Indian population, to detect a 15% change in the risk for breast cancer, nearly four thousand patients and an equal number of healthy controls would be needed to achieve a power of 80% (at α = 0.05)." (PMID 21829601, 2011). "Findings of the Breast Cancer Association Consortium, the only large scale study that has clearly addressed this possibility, favor such a hypothesis and place those with TGFB1*CC genotype at a higher risk of the disease." (PMID 21829601, 2011). "TGFB1 T29C polymorphism and risk for breast cancer in Maharashtrian and Parsi women." (PMID 21829601, 2011). "Basal-B lines were characterized by markers associated with aggressive tumor features, including PLAT (plasminogen activator) and TGFB1, as well as marker phenotypes associated with normal breast and breast cancer progenitor/stem cells (MUC−/CALLA+; CD44+/CD24−/low; and ITGB3(CD61)+)." (PMID 19582160, 2009). "For example, the TGFB1 -509C>T and rs1982073 (or rs1800470) polymorphisms have been shown to be associated with breast cancer survival in a Chinese population and chemoradiotherapy response in 175 Finnish patients with head and neck squamous cancer, respectively." (PMID 19566948, 2009). "BCAC also analyzed data from 12 studies for 16 SNPs in various candidate genes and concluded that only 5 SNPS (CASP8 D302H, IGFBP3-202 c > a, PGRV660L, SOD2 V16A, and TGFB1 L10P) were associated with breast cancer, but the statistical significance of the association was only borderline." (PMID 21655367, 2008). "A combined analysis of two UK breast cancer patient studies shows that 8% of patients are homozygous (TT) for the TGFβ1 (C-509T) variant allele and have a 15-fold increased risk of fibrosis following radiotherapy (95% confidence interval: 3.76–60.3; P=0.000003) compared with (CC) homozygotes." (PMID 17325707, 2007). "However, we observed an inverse association between the -509 C/T polymorphism of TGFB1 (p-trend = 0.04), which was stronger and more significant among women with estrogen receptor positive breast cancer." (PMID 17848193, 2007). "Besides these physiological functions, there is considerable evidence that TGFβ1 is implicated in several aspects of breast cancer onset and progression." (PMID 16404434, 2006). "Thus, detection of exosome- associated TGFβ1 levels could be a potential new method for predicting therapeutic response to trastuzumab-targeted therapy in HER2-positive breast cancer." (PMID 36276152, 2022). "Finally, we observed a significant association between KLK6 and TGFβ1, which may be one mechanism by which these molecules interact during lactation to influence future breast cancer risk." (PMID 22436421, 2012).
breast cancer (continued). "The cellular changes observed in TGFβ1-induced MCF-7 breast cancer epithelial cells resembled tumor cells undergoing EMT, E-cadherin expression, which was decreased in TGFβ1-induced cells, was increased by EO treatment." (PMID 40233022, 2025). "TGFβ1 upregulates CXCR4 expression in breast cancer cells and plays a prominent role in metastasis by enhancing angiogenesis and suppressing immune surveillance at secondary metastatic sites." (PMID 40075611, 2025). "Cdk5 has been identified as a key regulator of this process in breast cancer cells stimulated with transforming growth factor beta 1 (TGF-β1), a major inducer of EMT." (PMID 41369365, 2025). "It was also shown that GR is a required effector of TGFβ1-induced p38 MAPK signalling to advanced cancer phenotypes in TN breast cancer through regulation of cell migration." (PMID 39905197, 2025). "In breast cancers, under the influence of tumor-induced transforming growth factor β1 (TGFβ1), adipose tissue-derived mesenchymal stem cells (ADSCs) have been transdifferentiated into CAF phenotypes." (PMID 40805183, 2025). "Analysis revealed that both univariate (p = 0.01) and multivariate (p = 0.013) models showed serum TGFB1 levels that have a positive prognostic impact on overall survival in breast cancer patients." (PMID 41373732, 2025). "Transforming growth factor-beta 1 (TGF-β1) is strongly linked to cancer invasion and metastasis in advanced-stage breast cancer." (PMID 41020838, 2025). "AVID200 is a selective trap of TGFβ1 and TGFβ3 that has shown antitumor efficacy in breast cancer models in mice (4T1 cells)." (PMID 38256140, 2024). "The results revealed an up-regulation of TGFB1 expression in various tumors, including breast cancer, cholangiocarcinoma, and esophageal carcinoma." (PMID 39449805, 2024). "To validate these shRNA against Tgfb1, we transduced mouse cells of the 4T1 breast cancer cell line with lentiviral particles." (PMID 39765733, 2024). "As a result, TGFB1 can promote targeted migration of breast cancer cells through the lymphatic system, inhibit lymphatic growth and promote vascular angiogenesis, or contribute to resistance in endocrine-related cancers." (PMID 39468555, 2024). "Previously, we reported that TGFβ1-induced EMT promotes lymphatic dissemination of breast cancer cells by activating CCL21/CCR7-mediated chemotaxis." (PMID 38055067, 2023). "Together, the data suggested that IL7 produced and secreted by lymphatic endothelial cells exposed to TGFβ1 can act as a chemotactic factor for breast cancer cells with mesenchymal properties." (PMID 38055067, 2023). "Remarkably, a study conducted on breast cancer corroborated the ability of RES to impede EMT by modulating the activity of transforming growth factor-beta 1 (TGF-β1)." (PMID 37345095, 2023). "Recently, we reported that TGFβ1 stimulated breast cancer cells with mesenchymal properties to migrate in a targeted fashion towards the lymphatic system via CCR7/CCL21-mediated chemotaxis, similar to dendritic cells during inflammation." (PMID 38055067, 2023). "Emodin, a Chinese herbal medicine, exerts anti-tumorigenic impacts on breast cancer by suppressing the production of transforming growth factor beta 1 (TGFβ1) in macrophages." (PMID 37525217, 2023). "The genes were found to be associated with critical pathways such as TGFB1, Hippo and MAPK signalling pathways and focal adhesion-related pathways, which are involved in the development of breast cancer." (PMID 37875591, 2023). "A recent study showed that the enhanced promoter activity driven by the main allele is reduced after knocking down Fam98b, revealing the importance of Fam98b in expression of the TGFβ1 gene in breast cancer." (PMID 37919785, 2023). "It is known that a long treatment with TGFβ1 induces CSCs and drug resistance, while a shorter stimulation facilitates lung colonization by breast cancer cells." (PMID 36594086, 2023).
breast cancer (continued). "Our findings also suggest that SDC1 regulates the migration of MDA-MB-231 breast cancer cells through a TGFb1-Smad and E-cadherin-dependent mechanism." (PMID 37069585, 2023). "The results indicated that TGFβ1 stimulates SV-LECs to produce chemotactic factors that promote invasion of breast cancer cells with mesenchymal properties." (PMID 38055067, 2023). "Smad3, a transcription factor, upregulates the transcription of PTHLH by binding to the proximal PTHLH promoter region in response to TGFβ1 signalling in breast cancer cells and consequently promotes bone metastasis." (PMID 35406121, 2022). "Taken together, these data have shown that during CP-induced LLPS, the expression of TGFβ1 was significantly downregulated in 4T1 breast cancer cells." (PMID 36209170, 2022). "Macrophage TNF and TGFβ1 present within co-cultures have also been shown to increase the migration of MDA-231 breast cancer cells in a 3D culture model through MMP1 and MT1-MMP, respectively." (PMID 35359423, 2022). "In advanced breast cancer, transforming growth factor beta 1 (TGF‐β1) has been suggested to promote tumour progression by modulating the epithelial‐mesenchymal transition of cancer cells and promoting invasion, migration and metastasis." (PMID 35090088, 2022). "In this study we showed that TGFβ-1 treatment of breast cancer cells MCF7 is followed by elevated PM localization of activated H-ras and K-ras." (PMID 35931724, 2022). "They found that HER2-positive breast cancer cells express neuromedin U(NmU), which blocks the immune response and promotes the expression of immunosuppressive molecules, such as TGFβ1., therefore functionally affecting ADCC and inducing trastuzumab resistance." (PMID 36276152, 2022). "For example, in almost 4000 breast cancer cases in Europe, SNP rs1982073 (29T>C) was found in the coding sequence of the TGFB1 gene, which adds a second target site for miR-187." (PMID 36497229, 2022). "In a study conducted in women diagnosed with breast cancer, an increased amount of the TGFB1 transcript promoted development of cancer stem cells and additionally improved their resistance to chemotherapy." (PMID 35798776, 2022). "Breast cancer cells secrete TGFβ1 into the tumor stroma, where the growth factor is sensed by bone marrow-derived stromal cells, which leads to a Smad4-dependent induction of TNW in the stromal cells." (PMID 35785162, 2022). "Further, both NR2F1 and TGFB1 gene expressions were significantly higher in bone metastatic derivatives compared with wild-type 4T1 murine breast cancer cells." (PMID 35740627, 2022). "Evidence for Wnt5A crosstalk with TGFβ1 was shown in mammary gland development and breast cancer, given that Wnt5A was required for TGF-β acting through antagonizing β-catenin, thereby limiting mammary gland morphogenesis." (PMID 35053353, 2022). "Activated Smad3 promotes the transcription of PTHLH in response to TGFβ1, which is also known as a cachexia-inducing factor, in breast cancer." (PMID 35406121, 2022). "Leptin can also signal through TGFB1 in breast cancer, which promotes metastasis and cancer stem cells behavior." (PMID 34202922, 2021). "TGFB1 plays many roles in breast cancer, however, these functions can be both tumor suppressive and tumor promoting." (PMID 34771552, 2021). "It was demonstrated that TGFB induced migration via PTEN suppression, where TGFB1 switched breast cancer cells from a collective to a single cell migration mode via RHO/ROCK signaling." (PMID 34680293, 2021). "In early cancer development, TGFB1 can disrupt the cell cycle in breast cancer cells to induce apoptosis to inhibit growth and suppress tumor development." (PMID 34771552, 2021). "TGFβ1 induces overexpression of IL-6 in TAMs and T cells which are involved in the poor survival of breast cancer." (PMID 34220337, 2021). "In summary, our results demonstrated that calycosin inhibited breast cancer cell progression by suppressing EMT via BATF/TGFβ1." (PMID 34096887, 2021).
breast cancer (continued). "Wound healing assay results showed that TGFβ1 knockdown significantly reduced the migration of BATF-overexpressing breast cancer cells compared to the corresponding controls." (PMID 34096887, 2021). "We found that the expression level of TGFB1 was positively correlated with the infiltration level of various immune cells in different breast cancer subtypes." (PMID 34485309, 2021). "Mammary tumor cells also produced transforming growth factor β1 (TGFβ1), which induced TNC expression in the surrounding stroma." (PMID 33790905, 2021). "We cloned P1, P2, or P3 sequences of the TGFβ1 gene promoter into luciferase reporter vectors and transfected the recombinant vectors into breast cancer cells." (PMID 34096887, 2021). "Overall, these findings highlighted that CAFs secreted TGFβ1 which triggered HOTAIR upregulation in breast cancer cells." (PMID 33511320, 2021). "In this process, TGFβ1 secreted by malignant breast cancer cells acts through a paracrine mechanism on BM-MSCs to induce the production of soluble MMP14." (PMID 33804796, 2021). "Transwell invasion assay results showed that TGFβ1 knockdown significantly reduced the invasiveness of BATF-overexpressing breast cancer cells." (PMID 34096887, 2021). "Furthermore, genes such as TGFB1 that exhibit somatic mutations in patients with NTM are involved in breast cancer, and NTM infection may act as a potential risk factor for chronic inflammation and cellular transformation; several patients with NTM ultimately developed breast cancer." (PMID 34203447, 2021). "Our findings demonstrated that calycosin inhibited EMT and progression of breast cancer cells by suppressing BATF/TGFβ1 signaling." (PMID 34096887, 2021). "We used the TIMER database to further analyze the relationship between the expression level of TGFB1 and immune cell infiltration in different breast cancer subtypes." (PMID 34485309, 2021). "TIMAP expression is regulated by transforming growth factor beta 1 (TGFβ1); known for its role in breast cancer development and metastasis." (PMID 34181349, 2021). "TGFβ1-mediated activation of SMAD2/3/4 induced transcriptional upregulation of HOTAIR in breast cancer cells." (PMID 33511320, 2021). "Calycosin treatment significantly downregulated the levels of BATF and TGFβ1 transcripts and proteins in breast cancer cells." (PMID 34096887, 2021). "TGFβ1 treatment also significantly increased the migration and invasiveness of breast cancer cells, but calycosin reduced the migration and invasiveness of TGFβ1-treated breast cancer cells." (PMID 34096887, 2021). "In this article, BMP7 is shown to be able to antagonize the tumorigenic effect of TGFβ1 in breast cancer cells, by reducing the TGFβ1-induced activation of EMT-related genes, cell growth, and metastases." (PMID 33498521, 2021). "We identified TGFB1 as the most strongly regulated gene in ER + CAMA-1 breast cancer cells (> 25-fold down-regulation in Rab31 overexpressing cells)." (PMID 34906074, 2021). "In summary, our data demonstrated that calycosin inhibited in vitro migration, invasiveness and growth of breast cancer cells by suppressing BATF/ TGFβ1." (PMID 34096887, 2021). "We observed that overexpression of BATF upregulated TGFβ1 mRNA and protein levels in breast cancer cells, whereas, TGFβ1 knockdown decreased BATF mRNA and protein levels in BATF-overexpressing breast cancer cells." (PMID 34096887, 2021). "Recent studies found that the expression of TGFB1 genes were downregulated in breast cancer cells treated with curcumin." (PMID 34754622, 2021). "Our results demonstrated that TGFβ1 treatment increased in vitro migration and invasiveness of breast cancer cells by inducing EMT and increasing the expression of pro-metastatic proteins such as CD147, MMP2, and MMP9." (PMID 34096887, 2021). "As such, this work is specifically focused on the effects of TGFβ isoform (TGFβ1, β2, β3) signaling in the mammary environment and breast cancer." (PMID 34771508, 2021).
breast cancer (continued). "Transforming growth factor beta 1(TGF-β1) has been found to be highly associated with cancer invasion and metastasis in late-stage breast cancer." (PMID 34298639, 2021). "The cytokine transforming growth factor beta 1 (TGF-β1), which is a potent inducer of EMT, is upregulated in breast cancer tissues and associated with lymph metastasis and poor prognosis." (PMID 33271824, 2020). "Exosomes from anti-cancer drug-resistant breast cancer cells increase the levels of TGFβ1 and the lymphocyte activation inhibitor PD-L1 to confer resistance to anti-cancer drugs, such as trastuzumab." (PMID 32595638, 2020). "Treg induction has been shown to occur through the release of TGFβ1, ultimately protecting breast cancer cells from an immune attack." (PMID 32637408, 2020). "We found that RAC1B induced an increase in the levels of TGFβ1 mRNA and the secreted bioactive protein in pancreatic carcinoma Panc1 and breast cancer MDA-MB-231 cells." (PMID 33260366, 2020). "Mummy triggers inhibition of EMT and metastasis in breast cancer cells mainly through the downregulation of TGFβ1 activity, and more studies required to find its specific anticancer activity with details." (PMID 34466597, 2020). "A 24-gene pS134-GR-dependent signature induced by TGFβ1 predicts shortened overall survival in breast cancer patients." (PMID 32357907, 2020). "The increase in local mammary tumor recurrence in HFD offspring was linked to an increase in the markers of immunosuppression (Il17f, Tgfβ1, VEGFR2) in the tumor microenvironment (TME)." (PMID 32580156, 2020). "Transforming growth factor beta 1 (TGF-β1) is associated with epithelial-mesenchymal transition (EMT), lymph metastasis, and poor prognosis in breast cancer." (PMID 33271824, 2020). "TD-EVs-associated TGFβ1 suppressed the activity of NK cells by lowering the NKG2D expression in AML patients and suppressed T cell proliferation in breast cancer." (PMID 33260606, 2020). "Together, these results suggest that in pancreatic and breast carcinoma cells synthesis and secretion of bioactive TGFβ1 is positively controlled by RAC1B." (PMID 33260366, 2020). "To explore the factors that are responsible for inducing GREM1 expression in CAFs, we analyzed by data mining the expression of TGFB1/2/3 and inflammatory cytokines in breast cancer cell lines as well as in breast cancer tissues." (PMID 31533776, 2019). "The pronounced secretion of TGFβ1 by CAFs in breast cancer promotes an aggressive phenotype in tumor cells also through direct activation of EMT, with decreased expression of E-CADHERIN and over-expression of VIMENTIN, Fibronectin1 (FN1), MMP2 and MMP9." (PMID 30927908, 2019). "Tgfβ1 mRNA expression also was downregulated in the mammary tumors of TAM + JEKHT-treated rats, compared with the other two groups of rats." (PMID 30640711, 2019). "We showed that Dec1 expression is induced by HIF-1α in oral cancer cells under hypoxia, by TNFα in breast cancer cells under apoptosis, and by TGFβ1/pSmad3 in epithelial–mesenchymal transition of pancreatic cancer cells." (PMID 31597354, 2019). "TGFB1: It has been reported that individuals with the AG genotype of SNP rs334348 in the 3′UTR of TGFBR1 are more prone to breast cancer (OR = 2.2; CI 1.29–4.07; p = 0.005)." (PMID 30897768, 2019). "TGFβ1 secreted by CAFs induces epithelial-mesenchymal transition and metastasis of breast cancer through HOTAIR." (PMID 31448238, 2019). "We give insights into the roles of HGF and TGFβ1 in determining Twist and Snail profile at the center and invasive front of bone metastasis from breast carcinoma." (PMID 31121879, 2019). "Transforming growth factor beta 1 (TGFβ1) is one major player in this process and has been described as a double edged sword in breast cancer." (PMID 30004628, 2018). "MCF-7 (epithelial-luminal subtype) breast cancer cells were transformed into mesenchymal phenotype by long-term treatment with TGFβ (1 ng/mL for 16 days)." (PMID 30619759, 2018).